RNU6-453P (RNA, U6 small nuclear 453, pseudogene)
Gene: Small nuclear RNA gene on chromosome 17 (44,307,088 to 44,307,172, forward strand). Ensembl gene ENSG00000252628.
Homologues: Orthologues: rabbit U6 (66% identical), mouse Gm22540 (58% identical). Paralogues in human: RNU6-1024P (76% identical), RNU6-1075P (75% identical), RNU6-797P (75% identical), RNU6-869P (75% identical), RNU6-905P (75% identical), RNU6-1011P (74% identical), RNU6-106P (74% identical), RNU6-1124P (74% identical), RNU6-12P (74% identical), RNU6-13P (74% identical), RNU6-16P (74% identical), RNU6-24P (74% identical), and 1282 more.